RN7SL16P (RNA, 7SL, cytoplasmic 16, pseudogene)
Gene: Miscellaneous RNA gene on chromosome 4 (24,563,193 to 24,563,461, reverse strand). Ensembl gene ENSG00000243005.
Homologues: Orthologues: chimpanzee Metazoa_SRP (100% identical), macaque Metazoa_SRP (84% identical), pig Metazoa_SRP (70% identical). Paralogues in human: RN7SL1 (78% identical), RN7SL679P (78% identical), RN7SL2 (77% identical), RN7SL3 (77% identical), RN7SL14P (75% identical), RN7SL664P (75% identical), RN7SL336P (75% identical), RN7SL473P (75% identical), RN7SL492P (75% identical), RN7SL543P (75% identical), RN7SL126P (75% identical), RN7SL566P (75% identical), and 702 more.